CCDC88B (coiled-coil and HOOK domain protein 88B)
Description:
Acts as a positive regulator of T-cell maturation and inflammatory function. Required for several functions of T-cells, in both the CD4(+) and the CD8(+) compartments and this includes expression of cell surface markers of activation, proliferation, and cytokine production in response to specific or non-specific stimulation (By similarity). Enhances NK cell cytotoxicity by positively regulating polarization of microtubule-organizing center (MTOC) to cytotoxic synapse, lytic granule transport along microtubules, and dynein-mediated clustering to MTOC. Interacts with HSPA5 and stabilizes the interaction between HSPA5 and ERN1, leading to suppression of ERN1-induced JNK activation and endoplasmic reticulum stress-induced apoptosis.
Synonyms: HkRP3; BRLZ; FLJ37970; FLJ00354; GIPIE; CCDC88
Tractability: Antibody: UniProt places it where antibodies can reach, with high confidence. PROTAC: ubiquitination databases record sites on it; its protein half-life has been measured.
Gene: Protein-coding gene on chromosome 11 (64,340,204 to 64,357,534, forward strand). Ensembl gene ENSG00000168071.
Subcellular location: Membrane; Cytoplasm, cytoskeleton, microtubule organizing center; Endoplasmic reticulum; Golgi apparatus; Cytoplasm
Subcellular location (Human Protein Atlas): Centrosome; Cytosol; Nucleoplasm
Gene Ontology:
Molecular function: protein binding; dynein light intermediate chain binding; microtubule binding
Biological process: cytoplasmic microtubule organization; cytoskeleton-dependent intracellular transport; positive regulation of cytokine production; positive regulation of T cell activation; positive regulation of T cell proliferation; defense response to protozoan
Cellular component: centrosome; cytosol; membrane; cytoplasm; endoplasmic reticulum; Golgi apparatus; microtubule organizing center
Genetic constraint (gnomAD): Loss-of-function variants: 138 observed, 157.54 expected, observed/expected ratio (o/e) 0.88, 90% interval 0.76 to 1.01. The upper end of that interval is the gene's LOEUF score, 1.01, which puts it in group 4 of 6, group 1 being the genes least tolerant of losing a copy. Missense variants: 1,821 observed, 1,788.9 expected, observed/expected ratio (o/e) 1.02, 90% interval 0.98 to 1.06. Synonymous variants: 835 observed, 758.56 expected, observed/expected ratio (o/e) 1.1, 90% interval 1.04 to 1.17.
Homologues: Orthologues: chimpanzee CCDC88B (99% identical), macaque CCDC88B (95% identical), pig CCDC88B (83% identical), dog CCDC88B (81% identical), mouse Ccdc88b (78% identical), rat Ccdc88b (78% identical), guinea pig CCDC88B (77% identical), zebrafish ccdc88b (30% identical), Drosophila melanogaster Girdin (19% identical), Caenorhabditis elegans grdn-1 (16% identical), Caenorhabditis elegans zyg-12 (9% identical), Drosophila melanogaster hook (8% identical). Paralogues in human: CCDC88C (29% identical), CCDC88A (29% identical), HOOK1 (10% identical), HOOK2 (10% identical), HOOK3 (10% identical).
Diseases named in the same sentence as CCDC88B in open-access papers:
CCDC88B is named in the same sentence as 20 diseases in open-access papers, as found by Europe PMC text mining. Sharing a sentence is not in itself a finding about the gene and the disease. The quoted sentences say what the papers report.
sarcoidosis (5 papers, 2014 to 2025). Sarcoidosis is a multisystemic disorder of unknown cause characterized by the formation of immune granulomas in involved organs. "Previous studies revealed abnormal expression of CCDC88B was associated with susceptibility to several autoimmune disorder, including sarcoidosis, IBD, psoriasis, multiple sclerosis, and PBC." (PMID 40727246, 2025). "CCDC88B, from the same family, was suggested as the most promising candidate gene at location 11q13.1 in humans for susceptibility to Sarcoidosis (a complex inflammatory disease)." (PMID 24523889, 2014). "Overall, SNPs from the following genes have already been identified in previous studies on sarcoidosis (GWAS or other): CCDC88B, ANXA11, IL23R, FAM117B, CCL24, ATXN2/SH2B3." (PMID 41466414, 2025). "Among them, there were 14 genes (ABT1, BTN2A2, C2orf74, CCDC88B, FAM213A, MDH2, METTL21B, PRSS16, RP3-473L9.4, TCF19, TSFM, UBASH3A, UQCC2, ZSCAN26) associated with sarcoidosis risk consistently across these tissues." (PMID 40075078, 2025). "Among these, both GWAS and TWAS found a potential role of CCDC88B in sarcoidosis." (PMID 40075078, 2025). "In addition, our TWAS pinpointed many tissue-specific sarcoidosis-associated genes and found expressions of 14 genes (ABT1, BTN2A2, C2orf74, CCDC88B, FAM213A, MDH2, METTL21B, PRSS16, RP3-473L9.4, TCF19, TSFM, UBASH3A, UQCC2, ZSCAN26) associated with sarcoidosis across all three target tissues." (PMID 40075078, 2025). "Among those, CCDC88B and ANXA11 are potential regulators of apoptosis, whereas CCL24 was increased in broncho-alveolar lavage (BAL) of patients with stage 3 sarcoidosis compared to patients with Lo ̈ fgren syndrome and IL23R has been implicated in the formation of granulomas." (PMID 41466414, 2025).
colitis (4 papers, 2017 to 2024). Inflammation of the colon. "Further research has shown that the deficiency of CCDC88B in immune cells can markedly diminish the inflammatory injury of the intestinal epithelial barrier and play an anti-colitis role." (PMID 34737744, 2021). "Loss of Ccdc88b protects against DSS-induced colitis, with fewer pathological lesions and reduced intestinal inflammation in Ccdc88b-deficient mice." (PMID 29030607, 2017). "CCDC88B acts as a positive regulator of T-cell maturation and inflammatory function and loss of CCDC88B has been shown to protect against DSS-induced colitis in CCDC88B-deficient mice." (PMID 39505854, 2024). "CCDC88B physically interacts with ARHGEF2 and RASAL3; defective mice show dampened neuroinflammation, altered susceptibility to colitis and altered DCs motility by modulating RHOA, with ARHGEF2 and RASAL3 acting in opposite regulatory fashions." (PMID 38200184, 2024). "Here the authors show that Ccdc88b inactivation in T cells prevents colitis in a transfer model, and detect high colonic levels of CCDC88b in patients with Crohn disease or ulcerative colitis, identifying that expression correlates with disease risk." (PMID 29030607, 2017). "To investigate the tissue and cell types that express Ccdc88b in the colon during colitis, we performed immunohistochemistry and found Ccdc88b staining in a sub-population of cells that are also positive for the hematopoietic marker CD45." (PMID 29030607, 2017). "Here we show that a mutation in Ccdc88b protects mice against experimental intestinal colitis, both in the DSS-colitis and CD4 T cells transfer models." (PMID 29030607, 2017). "Here, we show that Ccdc88b+ lymphoid and myeloid cells are recruited to the site of inflammation in experimental colitis." (PMID 29030607, 2017). "Our results indicate that Ccdc88b is required for the induction of gut inflammation in the T cell transfer model of colitis." (PMID 29030607, 2017). "We examined the effect of Ccdc88b mutation on the capacity of naïve CD4+ T cell (CD4+CD45RBhi cells,) to induce colitis upon adaptive transfer into lymphopenic mice." (PMID 29030607, 2017). "Similarly, CCDC88B-positive lymphocytes and myeloid cells were distinctly increased in the inflammatory tissues from a dextran sodium sulfate-induced mouse colitis model." (PMID 34737744, 2021). "Also, the Rasal3 mutation causes a unique susceptibility to colitis-associated colorectal cancer phenotype not seen in the Ccdc88b or Arhgef2 mutants." (PMID 38200184, 2024). "In addition, CCDC88B was also involved in the occurrence of inflammatory diseases such as colitis." (PMID 34737744, 2021). "In a T cell transfer model of colitis, Ccdc88b mutant CD4+ T cells do not induce colitis in immunocompromised hosts." (PMID 29030607, 2017). "We found that Rag1−/− mice lacking functional Ccdc88b recovered from DSS-induced colitis (increased body weight, lower colonic damage, better total pathology scores) faster and more fully when compared to control Rag1−/− mice." (PMID 29030607, 2017). "Likewise, in a T cell transfer model, Ccdc88b-deficent T cells do not induce colitis in immunocompromised Rag1−/− mice." (PMID 38200184, 2024). "To directly assess whether CCDC88B plays a functional role in colitis, we subjected WT and Ccdc88b mutant (Ccdc88bmut) mice to 3% DSS for 5 days followed by water for 3 days and evaluated colitis incidence." (PMID 29030607, 2017). "Furthermore, Cccdc88b mutant mice are protected against DSS-induced colitis, and naive Ccdc88b mutant CD4+ T cells do not induce colitis in immunocompromised mice." (PMID 29030607, 2017).
colorectal cancer (3 papers, 2017 to 2024). A primary or metastatic malignant neoplasm that affects the colon or rectum. "It has been reported that CCDC88B has a critical function in colon inflammation and the pathogenesis of IBD, and a previous study proved that patients with IBD have a higher probability of developing colorectal cancer than other people." (PMID 32812032, 2020). "We further evaluated CCDC88B mRNA and protein levels in colon surgical specimens obtained from UC patients (UC; n = 46) and CD patients (CD; n = 11), and from normal controls, consisting of non-inflamed areas of the colon of patients with colorectal cancer or diverticulitis (n = 73)." (PMID 29030607, 2017).
Crohn disease (3 papers, 2017 to 2024). A gastrointestinal disorder characterized by chronic inflammation involving all layers of the intestinal wall, noncaseating granulomas affecting the intestinal wall and regional lymph nodes, and transmural fibrosis. "In a cohort of patients with Crohn’s disease, CCDC88B expression correlates positively with disease risk." (PMID 29030607, 2017). "Furthermore, expression of CCDC88B mRNA is regulated by cis-acting variants in CD14+ myeloid cells, with CCDC88B mRNA expression correlated positively with disease risk in a cohort of Crohn’s disease patients." (PMID 38200184, 2024). "For example, CCDC88B expression was significantly elevated in lymphatic and myeloid cells of the colon lamina propria in patients with ulcerative colitis and Crohn’s disease." (PMID 34737744, 2021).
inflammatory bowel disease (2 papers, 2017 to 2020). A spectrum of small and large bowel inflammatory diseases of unknown etiology. "Another interesting gene identified by GWAS was CCDC88B (coiled-coil domain-containing protein 88B) located on chromosome 11q13, which encodes a positive regulator of T-cell maturation and inflammatory function involved in inflammatory bowel diseases." (PMID 32823753, 2020). "Hook-related protein family member CCDC88b is encoded by a locus that has been associated with inflammatory bowel disease." (PMID 29030607, 2017).
hypothyroidism (1 paper, 2025). Abnormally low levels of thyroid hormone. "We demonstrated causal association between PBC and hypothyroidism, and then further results revealed that CCDC88B and MMEL1 were two potential drug targets for hypothyroidism." (PMID 40727246, 2025). "In summary, we found the correlation between the expression of CCDC88B, MMEL1, and hypothyroidism risk, which indicated potential drug targets for hypothyroidism." (PMID 40727246, 2025). "Among the genes identified, CCDC88B and MMEL1 were found to have positive associations with the risk of hypothyroidism (CCDC88B: OR = 1.004, p=4.69E − 07; MMEL1: OR = 1.004, p=6.65E − 06) and FinnGen cohorts (CCDC88B: OR = 1.044; MMEL1: OR = 1.038)." (PMID 40727246, 2025). "The two genes may be the drug targets for hypothyroidism (CCDC88B: coloc.abf-PPH4 = 94.7%; MMEL1: coloc.abf-PPH4 = 91.8%)." (PMID 40727246, 2025). "Given these, CCDC88B may be a potential therapeutic target for hypothyroidism." (PMID 40727246, 2025). "Third, we identified CCDC88B and MMEL1 are potential drug targets for hypothyroidism, and experimental study and clinical trial should be performed to evaluate their therapeutic value." (PMID 40727246, 2025). "Although direct evidences on the correlation between CCDC88B and hypothyroidism have not been reported, its role in the activity and migration of immune cells suggests CCDC88B was involved in the disease." (PMID 40727246, 2025).
renal carcinoma (1 paper, 2025). A carcinoma arising from the epithelium of the renal parenchyma or the renal pelvis. "Nine intersecting genes were screened and used to construct a prognostic model, whereby seven key biomarkers—MXD3, PLCB2, CCDC88B, DEF6, IFNG, TBC1D10C, and PLEKHN1—were significantly influenced the prognosis of renal cancer." (PMID 41357186, 2025).
cancer (2 papers, 2020 to 2022). A tumor composed of atypical neoplastic, often pleomorphic cells that invade other tissues. "We found that 30 of these genes which included Nckap1l, Ncf1, Pla2g15, Unc93b1, Lrrc33, Rgs10, Gmfg, Rbm25, C3ar1, Ccdc88b, Fam105a, Gng11, Phc1, Rasa4, Dag1, Tyrobp, Tmsb4x, Cfp, Prkd1, Gp49a, Trem2, C1qc, Lyz2, Igfbp7, Rab30, Cxcl16, Egfl7, Ube2r2, Pltp, and Cfb, showed a relation with cancer." (PMID 32812032, 2020). "It is notable that the top genes from an overall cancer vs control comparison included GATA4, CCDC88B, and WAS." (PMID 35202405, 2022).
cardiovascular disease (1 paper, 2021). "Additionally, different loci in the CCDC88B gene have been also associated with cardiovascular disease in the same dataset (p-value = 1x10-10)." (PMID 34714828, 2021).
tumor (1 paper, 2017). "In addition, CCDC88B (HkRP3) is required for NK cells cytotoxicity and anti-tumor activity in general, and for the production and mobilization of cytotoxic granules in these cells." (PMID 29030607, 2017).
CCDC88B also shares sentences with these, for which no sentence is quoted: ulcerative colitis (2 papers); autoimmune disorder (1); cerebral malaria (1); diverticulitis (1); Granuloma (1); inflammation (1); multiple sclerosis (1); psoriasis (1); skin cancer (1); T cell deficiency (1).